NECTIN1 (nectin cell adhesion molecule 1)
Description:
Cell adhesion molecule that promotes cell-cell contacts and plays important roles in the development of the nervous system. Acts by forming homophilic or heterophilic trans-dimers. Heterophilic interactions have been detected between NECTIN1 and NECTIN3 and between NECTIN1 and NECTIN4 (By similarity). Involved in axon guidance by promoting contacts between the commissural axons and the floor plate cells (By similarity). Involved in synaptogegesis (By similarity). Has some neurite outgrowth-promoting activity (By similarity). Promotes formation of checkerboard-like cellular pattern of hair cells and supporting cells in the auditory epithelium via heterophilic interaction with NECTIN3: NECTIN1 is present in the membrane of hair cells and associates with NECTIN3 on supporting cells, thereby mediating heterotypic adhesion between these two cell types (By similarity). Required for enamel mineralization (By similarity). (Microbial infection) Acts as a receptor for herpes simplex virus 1/HHV-1, herpes simplex virus 2/HHV-2, and pseudorabies virus/PRV. Constitutes the major receptor for herpes simplex virus 1/HHV-1 entry into host cells.
Synonyms: HveC; HIgR; CD111; PRR1; PVRL1; PRR; PVRR1; SK-12; CLPED1; OFC7; Nectin-1; ED4; HV1S; PVRR
Tractability: Antibody: UniProt places it where antibodies can reach, with high confidence; its Gene Ontology location is reachable by antibodies, with high confidence; UniProt predicts a signal peptide or a membrane-spanning region. PROTAC: UniProt records ubiquitination sites on it; ubiquitination databases record sites on it.
Gene: Protein-coding gene on chromosome 11 (119,623,408 to 119,729,200, reverse strand). Ensembl gene ENSG00000110400.
Subcellular location: Cell membrane; Cell junction, adherens junction; Presynaptic cell membrane; Cell membrane (Isoform Alpha); Cell membrane (Isoform Delta); Secreted (Isoform Gamma)
Pathways (Reactome):
Cell-Cell communication: Adherens junctions interactions; Nectin/Necl trans heterodimerization
Gene Ontology:
Molecular function: cell adhesion mediator activity; cell adhesion molecule binding; identical protein binding; protein binding; virus receptor activity; coreceptor activity; carbohydrate binding; protein homodimerization activity; protein-containing complex binding; signaling receptor activity; virion binding
Biological process: heterophilic cell-cell adhesion; homophilic cell-cell adhesion; symbiont entry into host cell; cell adhesion; cell-cell adhesion; cochlea morphogenesis; immune response; protein localization to cell junction; axon guidance; regulation of synapse assembly; regulation of synapse organization
Cellular component: adherens junction; extracellular region; plasma membrane; apical junction complex; membrane; presynaptic membrane; axon; cell-cell contact zone; dendrite; growth cone membrane; hippocampal mossy fiber to CA3 synapse; presynaptic active zone membrane
Genetic constraint (gnomAD): Loss-of-function variants: 23 observed, 49.47 expected, observed/expected ratio (o/e) 0.46, 90% interval 0.33 to 0.66. The upper end of that interval is the gene's LOEUF score, 0.66, which puts it in group 2 of 6, group 1 being the genes least tolerant of losing a copy. Missense variants: 591 observed, 736.78 expected, observed/expected ratio (o/e) 0.8, 90% interval 0.75 to 0.86. Synonymous variants: 270 observed, 298.37 expected, observed/expected ratio (o/e) 0.9, 90% interval 0.82 to 1.
Gene-disease validity (ClinGen):
ClinGen rates the evidence that NECTIN1 causes each of these diseases.
cleft lip/palate-ectodermal dysplasia syndrome (autosomal recessive): Definitive.
Homologues: Orthologues: chimpanzee NECTIN1 (99% identical), macaque NECTIN1 (99% identical), dog NECTIN1 (97% identical), rat Nectin1 (95% identical), mouse Nectin1 (95% identical), rabbit NECTIN1 (94% identical), pig NECTIN1 (78% identical), guinea pig NECTIN1 (69% identical), tropical clawed frog nectin1 (63% identical), zebrafish nectin1b (51% identical), zebrafish nectin1a (46% identical), Drosophila melanogaster Fas3 (14% identical), and 2 more. Paralogues in human: NECTIN3 (30% identical), NECTIN2 (29% identical), PVR (23% identical), NECTIN4 (22% identical), CADM3 (19% identical), CADM2 (17% identical), CADM4 (17% identical), CADM1 (16% identical), CD226 (12% identical), CD200 (12% identical), CRTAM (12% identical), TIGIT (8% identical), and 2 more.
Diseases named in the same sentence as NECTIN1 in open-access papers:
NECTIN1 is named in the same sentence as 90 diseases in open-access papers, as found by Europe PMC text mining. Sharing a sentence is not in itself a finding about the gene and the disease. The quoted sentences say what the papers report.
melanoma (12 papers, 2011 to 2025). A malignant, usually aggressive tumor composed of atypical, neoplastic melanocytes. "Together, these results show that NECTIN1 loss prevents adherens junction formation between melanoma cells and promotes their migration specifically under serum depletion." (PMID 36229674, 2022). "Although biallelic loss of NECTIN1 was detected in 4.4% of cases (16 cases), half of melanomas exhibited shallow deletions (186 cases) totaling an overall frequency of deletion of 55%." (PMID 36229674, 2022). "By adding Matrigel to transwells, similar differences were measured between NECTIN1-wild-type and deficient cells, indicating that NECTIN1 loss increases both 2D migration and 3D invasion of melanoma cells." (PMID 36229674, 2022). "We sought to identify the serum components responsible for the difference in cell behavior between NECTIN1-proficient and deficient melanoma cells." (PMID 36229674, 2022). "Focal adhesion kinase (FAK, also known as PTK2) was the most differentially activated kinase between NECTIN1-deficient and proficient A375 melanoma cells." (PMID 36229674, 2022). "We found that NECTIN1 loss stimulates melanoma cell migration in vitro and spreading in vivo in both zebrafish and human tumors specifically in response to decreased IGF1 signaling." (PMID 36229674, 2022). "We found that NECTIN1 loss changes the response of melanoma cells to microenvironmental insulin-like growth factor 1 (IGF1) signaling by controlling a switch from cell–cell adhesion to cell–matrix adhesion." (PMID 36229674, 2022). "In conclusion, high Nectin-1 expression was associated with a more pronounced susceptibility to T-VEC mediated oncolysis in malignant melanoma cell lines." (PMID 34205379, 2021). "Moreover, forced IGF1 signaling partially reversed the migratory propensity of NECTIN1-deficient cells in the modified transwell assay in 6 different human melanoma cell lines, similar to direct treatment with IGF1 itself." (PMID 36229674, 2022). "Loss of NECTIN1 is a frequent event in human melanoma and is associated with metastasis." (PMID 36229674, 2022). "T‐VEC, an HSV‐1‐based oncolytic therapy, has demonstrated efficacy in melanoma, partially attributable to the elevated expression of its cognate receptor Nectin‐1 on melanoma cells." (PMID 41053536, 2025). "In this study, we used a modified B16 melanoma mouse model (B16-C10) expressing nectin-1, a human receptor for BHV-1 entry, to further investigate oBHV anti-tumor immunostimulatory properties." (PMID 36831636, 2023). "To overcome the lack of syngeneic mouse models susceptible to oBHV, we used B16-C10 cells, genetically engineered B16 mouse melanoma cells expressing nectin-1, a human BHV-1 entry receptor." (PMID 36831636, 2023). "Immunohistochemistry for NECTIN1 in human melanoma revealed that NECTIN1 protein levels were significantly lower in metastases compared to primary tumors." (PMID 36229674, 2022). "Here, we examined the role of the third most significant chromosomal deletion in human melanoma that inactivates the adherens junction gene NECTIN1 in 55% of cases." (PMID 36229674, 2022). "NECTIN1 has two orthologs in zebrafish, nectin1a and nectin1b, of which only nectin1b is substantially expressed in primary zebrafish melanomas." (PMID 36229674, 2022). "In low IGF1 conditions and in the presence of NECTIN1, melanoma cells form robust cell–cell contacts through adherens junctions, which prevent them from leaving the niche." (PMID 36229674, 2022). "Our study establishes NECTIN1 as a major determinant of melanoma dissemination and uncovers a genetic control of the response to microenvironmental signals." (PMID 36229674, 2022). "Metastases were overrepresented among samples with low NECTIN1 staining whereas samples with high NECTIN1 were enriched for primary melanomas." (PMID 36229674, 2022). "Together, these data nominate NECTIN1 as a frequently altered gene in melanoma with a potential role in metastasis." (PMID 36229674, 2022).
melanoma (continued). "By analyzing copy-number alterations in The Cancer Genome Atlas (TCGA) cohort of 363 human melanomas, we found that the third most significant focal deletion at chr11q23.3 only contained the gene NECTIN1." (PMID 36229674, 2022). "Surprisingly, western blot analysis of NECTIN1 and phospho-FAK revealed a positive correlation between FAK activity and NECTIN1 levels in our panel of 6 human melanoma cell lines." (PMID 36229674, 2022). "NECTIN1 mRNA expression correlated with linear copy number, with human melanoma samples with deep or shallow deletions of NECTIN1 expressing significantly less NECTIN1 mRNA than diploid samples." (PMID 36229674, 2022). "To evaluate the potential contribution of cell proliferation, we measured the growth of melanoma cells upon NECTIN1 manipulation." (PMID 36229674, 2022). "FAK blockade suppressed the migration of four out of five additional human melanoma cell lines upon NECTIN1 downregulation, demonstrating that most melanomas lacking NECTIN1 depend on FAK signaling to migrate." (PMID 36229674, 2022). "Our data show that NECTIN1 status determines the response of melanoma cells to environmental stress, specifically a drop in local IGF1 concentration." (PMID 36229674, 2022). "Our data demonstrate that baseline expression of Nectin-1 in melanoma metastasis correlates with the response to intralesional T-VEC therapy and can therefore be used as a biomarker." (PMID 34205379, 2021). "Since IHC is a widely used method for diagnostic purposes and is well established for biomarker assessment, we compared Nectin-1 expression in melanoma cell lines using FACS and IHC." (PMID 34205379, 2021). "Altogether, our study revealed Nectin-1 as suitable biomarker for the treatment of melanoma metastases using intratumoral T-VEC application." (PMID 34205379, 2021). "Overall, our data revealed heterogeneity of Nectin-1 expression in melanoma cell lines as well as in melanoma metastases." (PMID 34205379, 2021). "The results so far showed a predictive value of Nectin-1 expression, as evaluated by flow cytometry, for melanoma cell death upon T-VEC inoculation." (PMID 34205379, 2021). "Altogether, Nectin-1 served as biomarker for T-VEC-induced melanoma regression in vitro and in vivo." (PMID 34205379, 2021). "Altogether, our data support the role of Nectin-1 in pretreatment biopsies to guide clinical decision-making in malignant melanoma and supposedly other tumor entities." (PMID 34205379, 2021). "Our data indicate that Nectin-1 is a key molecule for the entry of oncolytic HSV-1 into malignant melanoma, thus confirming the results obtained in glioblastoma and other malignant tumors using cell lines and a xenograft tumor model." (PMID 34205379, 2021). "In fact, melanoma cell lines showed a higher percentage of Nectin-1 and HVEM expression, while cGAS and STING were more prominently expressed in melanoma metastasis." (PMID 34205379, 2021). "Both in cell lines and in melanoma metastases, the degree of Nectin-1 expression significantly correlated with tumor cell regression." (PMID 34205379, 2021). "The essential role of cholesterol for HSV-1 entry into Vero cells and mouse melanoma cells expressing either nectin-1 or HVEM has been shown." (PMID 22022400, 2011). "Recent studies suggest that lipid rafts act as platforms for HSV-1 entry into Vero cells and mouse melanoma cells expressing either nectin-1 or HVEM involving the interaction of gB with cellular components in the rafts." (PMID 22022400, 2011). "Here, we identified deletions of the gene NECTIN1 as a frequent driver of melanoma dissemination." (PMID 36229674, 2022). "In addition to melanoma, NECTIN1 is frequently deleted in bladder, uterine and cervical cancers in TCGA datasets." (PMID 36229674, 2022). "Nectin1 inactivation in primary zebrafish melanoma modestly accelerated tumor onset." (PMID 36229674, 2022). "We inactivated NECTIN1 by short hairpin RNA (shRNA) or CRISPR in the A375 human melanoma cell line." (PMID 36229674, 2022).
melanoma (continued). "In the absence of serum, NECTIN1-deficient colonies were significantly more dispersed in collagen-rich matrix, implying that NECTIN1 loss increases the spreading capacity of melanoma cells in a 3D environment." (PMID 36229674, 2022). "We identified NECTIN1 as a major metastasis-suppressor gene in melanoma." (PMID 36229674, 2022). "Further prospective studies are needed to determine the clinical threshold of Nectin-1 expression and additional parameters, which will allow the development of optimized personalized therapies for oncolytic herpes viruses in melanoma and other solid malignancies." (PMID 34205379, 2021). "Entry into neurons and Vero cells can occur via fusion at the plasma membrane at neutral pH while fusion with HeLa and CHO cells involves pH-dependent endocytosis, and fusion with C10 (B78-H1 mouse melanoma expressing nectin-1) cells involves pH-independent endocytosis." (PMID 22022400, 2011). "However, in B78 mouse melanoma cells, nectin-1 mediates HSV-1 uptake." (PMID 36173301, 2022). "We performed immunofluorescence in tissue sections of 20 human melanoma biopsies with markers of active IGF1 signaling (phospho-IGF1R) and adherens junctions (α-catenin) and independently evaluated NECTIN1 expression." (PMID 36229674, 2022). "To this end, we established Nectin-1, HVEM, STING, and cGAS immunostaining for our panel of 20 melanoma cell lines after embedding them into paraffin." (PMID 34205379, 2021). "To identify potential biomarkers for the oncolytic effect induced by T-VEC, we analyzed the expression of Nectin-1 and HVEM with respect to isotype controls on our melanoma cell lines using flow cytometry." (PMID 34205379, 2021). "Despite these limitations, both the in vitro and in vivo data of our study demonstrated an important predictive role of Nectin-1, a member of the immunoglobulin superfamily, for T-VEC-induced oncolysis of malignant melanoma." (PMID 34205379, 2021). "We have shown previously that human nectin-1 fused with GFP at the N-terminus is functional for cell adhesion and HSV infection in mouse melanoma B78H1 cells." (PMID 30759143, 2019). "Coimmunofluorescence in 20 human melanoma tissue sections also failed to reveal any correlation between NECTIN1 and E-cadherin protein levels." (PMID 36229674, 2022). "The only exception was in a melanoma that stained negative for NECTIN1 but expressed E-cadherin, which likely explains the ability to form adherens junctions." (PMID 36229674, 2022). "In human melanoma, NECTIN1 status did not correlate with the expression of E-cadherin, another adherens junction component whose loss has been linked to metastatic progression in multiple cancers." (PMID 36229674, 2022). "Similar migration differences were observed between NECTIN1-deficient and proficient cells in the presence or absence of different ECM proteins, suggesting that, in transwell assays, matrix is dispensable for the migration of melanoma cells lacking NECTIN1." (PMID 36229674, 2022). "NECTIN1 inactivation significantly increased melanoma cell migration following serum withdrawal in all cell lines, indicating that the function of NECTIN1 does not depend on melanoma differentiation state or basal migratory capacity." (PMID 36229674, 2022). "In human melanoma biopsy specimens, adherens junctions were seen exclusively in areas with low IGF1 levels, but not in NECTIN1-deficient tumors." (PMID 36229674, 2022). "Taken together, Nectin-1 expression levels in pretreatment biopsies of cutaneous melanoma metastases significantly predicted the response to T-VEC mediated oncolysis, which paralleled the results obtained with melanoma cell lines." (PMID 34205379, 2021). "We previously characterized mouse melanoma B78H1 cells, which are resistant to infection by HSV-1 and HSV-2 due to the absence of a functional entry receptor but become fully permissive upon expression of human HVEM or nectin-1." (PMID 31581238, 2019).
melanoma (continued). "Mutations were engineered in full-length nectin-1 and transfected into receptor-negative B78H1 mouse melanoma cells." (PMID 21980294, 2011). "In addition, our melanoma panel lacked cell lines harboring different STING levels in combination with high Nectin-1 expression, which would have supported an efficient infection." (PMID 34205379, 2021). "Moreover, an antibody blocking integrin α6β4, as well as small-molecule inhibitors of integrins αvβ3 and αvβ5, significantly decreased the migration of A375 cells lacking NECTIN1, directly implicating these integrins in the motility of adherens junction-incompetent melanoma cells." (PMID 36229674, 2022). "In the presence of high levels of IGF1, melanoma cells proliferate within the cancer cell niche regardless of NECTIN1 status, as demonstrated by previous reports examining the role of IGF1 in early melanoma lesions." (PMID 36229674, 2022). "In 20 melanoma cell lines, oncolytic activity of T-VEC was correlated with the expression of Nectin-1 but not HVEM, as evaluated via flow cytometry and immunohistochemistry." (PMID 34205379, 2021). "In the absence of HVEM, Nectin-1 seemed to compensate and mediate HSV-1 entry into melanoma cells." (PMID 34205379, 2021). "Direct comparison of Nectin-1 and HVEM indicated that the latter was less effective in promoting HSV-1 entry, which could explain why HVEM was not predictive of T-VEC induced melanoma cell death in our in vitro and in vivo studies." (PMID 34205379, 2021).
viral infection (12 papers, 2012 to 2025). "This should confer the binding with PRV gD an astonishing priority during the viral infection over nectin-1 dimerization, therefore exploiting its cell adhesion functions." (PMID 28542478, 2017). "They utilize the envelope glycoprotein D (gD) on the virion surface to interact with nectin-1, initiating the virus infection." (PMID 28542478, 2017). "Our results demonstrate that NECTIN1 is a novel factor restricting Flaviviridae family virus replication and highlight the complexity of virus-host interactions and the multifaceted nature of host factors involved in viral infection." (PMID 39570015, 2024). "Feline cell receptors other than SLAMF1 and nectin-1 might bind FeMV H glycoprotein in tissues, resulting in severe viral infection." (PMID 37896864, 2023). "Using HSV-1(KOS)Rid1, which only uses nectin-1 for entry and a murine model of corneal infection, we demonstrate that nectin-1 may be sufficient to allow virus infection of the eye and spread of the virus to the TG." (PMID 23213272, 2012). "The prospect of modulating nectins in and out of adherens junctions could be beneficial to viral infections other than HSV, such as the measles virus and polio virus as well as other types of skin disorders that involve nectin-1." (PMID 39599904, 2024). "Indeed, we reported that nectin-1, a receptor for herpes simplex virus-1, is hidden within the adherens and tight junctions of oral epithelium, and HIV-induced disruption of epithelial junctions exposes nectin-1 to herpes simplex virus-1, facilitating rapid viral infection and spread." (PMID 31869348, 2019).